CD163 (CD163 molecule)
Diseases named in the same sentence as CD163 in open-access papers (continued):
Sharing a sentence is not in itself a finding about the gene and the disease.
tumor (continued). "However, a recent study outlines the landscape of immune cells in HCC by single-cell RNA sequencing and revealed upregulation of CD163+ TAM in the tumor core and edge supporting the association of HCC, CD163 and prognosis." (PMID 32752088, 2020). "Once in the extracellular space, eNAMPT promotes differentiation of resting monocytes, polarizing them toward tumor-supporting M2 macrophages, which express high levels of CD163, CD206, and indoleamine 2,3-dioxygenase (IDO) and secrete immunosuppressive cytokines." (PMID 32155826, 2020). "Protumorigenic TAMs such as those that can be identified by dual staining with CD68 and CD163 are known to promote tumor cell proliferation, angiogenesis, invasion, and metastasis as well as to suppress T-cell–mediated antitumor immune responses through paracrine mechanisms." (PMID 32190817, 2020). "High M2 ratio (CD163+/CD68+) in the tumor stroma is a potential marker for predicting malignant clinical outcomes in NSCLC patients, and consideration of M2 ratio and VEGF-C expression in combination may enhance the accuracy of prognostic prediction." (PMID 33228719, 2020). "Compared with pre-treatment or with post-treatment samples from the Ipilimumab group, the combination enhanced the intratumoral endothelial activation, resulting in increased trafficking of CD8+ T cells and CD163+ dendritic macrophages across the tumor vasculature." (PMID 32793228, 2020). "In this study, a quantitative evaluation of macrophages infiltrating CHS tissues, using CD68 as a macrophage marker and CD163 as a marker of alternatively activated M2 macrophages was conducted and the results were compared with the intra-tumor microvessel density (iMVD)." (PMID 32344648, 2020). "As a less radical alternative to eradication of CD163+ TAMs, the macrophages might be reprogrammed from a tumor-promoting “M2-like” phenotype to a tumoricidal “M1-like” phenotype." (PMID 32752088, 2020). "Moreover, an association between higher CD80+/CD163+ cell ratio at the tumor invasive front and improved survival was found, as well as a protective role of CD80+ macrophages in preventing tumor relapse." (PMID 32650452, 2020). "The most distinctive group, named Tumor Associated Macrophages (TAM; 38% ± 13%) expressed CD16 and restricted lineage markers (CD68, CD163) and was consistently present in all tumor cases, but only occasionally in the non-neoplastic samples (Case #8 and 3 normal myometria, not shown)." (PMID 31959856, 2020). "In addition, the notable presence of TIGIT and its association with other immunosuppressive markers such as CD163 and PDL-1 suggest its possible role as a novel biomarker of an immunosuppressive tumor microenvironment in GBM." (PMID 32899203, 2020). "Therefore, it is important to distinguish CD163+ malignant cells and macrophages when investigating the influence of CD163 as a measure of tumor microenvironment and its influence on prognosis." (PMID 32752088, 2020). "Therefore, we decided to study CD163 in a broader context, comprising both the tumor microenvironment and circulation of CRC patients." (PMID 32824692, 2020). "Depletion of both monocyte derived CD163+ macrophages and tissue resident CD163+ Tim4+ macrophages by CD163-targeted lipid nanoparticles loaded with doxorubicin contributed to reduced tumor growth in omentum and reduced metastatic spread in the ascites and to the diaphragm." (PMID 32752088, 2020). "Interestingly, there was greatest CD163+ macrophage recruitment to the LNs in the control, tumor bearing mice that had negligible metastatic engraftment to the neck." (PMID 31685946, 2020). "The study was based on 107 TNC cases operated on at Dokkyo Medical University Hospital using the pan-macrophage marker CD68 and the M2 macrophage marker CD163 in the tumor stroma (TS) and tumor nest (TN), respectively, and examined the clinicopathological significance." (PMID 32607685, 2020).
tumor (continued). "In order to elucidate the biological and clinical significance of M2 TAMs, a comprehensive clinical study that assessed tissue distribution of CD163+ TAMs in tumor stroma, tumor islets, and alveolar space in 160 NSCLC patients from the Japanese cohort was performed." (PMID 33194645, 2020). "High expression of CD163 at tumor invasive front was significantly associated with tumor grade, LVI, TI, LNM and TNM stage (P < 0.05, respectively), while high expression of CD68 at tumor invasive front was only significantly associated with LNM (P = 0.016)." (PMID 30927925, 2019). "We found that tumor CD47 expression (HR = 1.703; p = 0.038), CD68+ M (HR = 1.853; p = 0.012), CD163+ M2 (HR = 1.898; p = 0.014), tumor diameter (HR = 1.626; p = 0.047), grade (HR = 1.745; p = 0.011), and N stage (HR = 1.831; p < 0.001) were independent factors associated with OS." (PMID 31771616, 2019). "To investigate the functional phenotype of TLR3-expressing macrophages, we analyzed by IHC analysis the expression of CD163, marker of M2 macrophages reported to function in immune suppression and also tumor progression, on a portion of NSCLC specimens whose material were available." (PMID 31582772, 2019). "Notably, our data revealed increased M2 macrophage markers, CD68 and CD163 and Arginase (Arg), immunoreactivity at the tumor stromal interface of PKTP PDAC, compared with the PKP model." (PMID 31109321, 2019). "Besides, downregulation of miR-130a was closely associated with tumour stage, metastasis, poor overall survival, and the presence of the tumour macrophage marker CD163 in the NSCLC samples." (PMID 30944831, 2019). "Several reports have shown that CD163+ M2 macrophages comprised the main population of the tumor-associated macrophages (TAMs) that play important roles for suppressing anti-tumor immune responses and serum levels of sCD163, generated by proteolytic shedding, is thought to be a marker for TAMs." (PMID 31192215, 2019). "Interestingly, the high number of CD68++CD163+ TAMs in close proximity to the tumor cell resulted in improved prognosis of patients in our cohort." (PMID 31477692, 2019). "A decrease in the ratio of CD163+ macrophages to F4/80+ macrophages upon OG treatment suggested that OG inhibited macrophage M2-polarization or/and M2-macrophage infiltration within the tumor." (PMID 31905895, 2019). "Three macrophage markers were used to detect tumor-associated macrophages: CD68, which is a pan-macrophage marker, CD163, which is considered to stain for tumor-associated macrophages polarized toward an M2 phenotype, and CD80, which is more associated with M1-like macrophages." (PMID 30879106, 2019). "Moreover, we identified significant coherences between PD-L1 expression in tumor-associated lymph follicles and the local abundance of tumor-associated macrophages (TAMs) (CD68+, CD163+)." (PMID 30899426, 2019). "Despite the locoregional heterogeneity, we found a significant positive association of the amounts of CD68‐, CD163‐ and CD206‐positive GAM subpopulations in the vital tumor core with prolonged overall survival of IDH1R132H‐non‐mutant GBM patients performing a median split for each M/M marker." (PMID 30506802, 2019). "IHC analyses further reveal that such tumor masses contained comparable levels of F4/80+ cells (pan macrophages), CD163+ cells (M2-macrophages), and CD204+ cells (M2-macrophages), suggesting that EndoMT-mediated tumor promotion was associated with infiltrating M2-macrophages." (PMID 31847880, 2019). "In the present study, we performed a comprehensive comparison between HHLA2 and PD-L1 in terms of the expression pattern, clinical relevance and their associations with tumor infiltrating CD3+, CD8+, CD4 + Foxp3+, CD68+, CD163+ and CD20+ immune cells in a ICC cohort after curative resection." (PMID 30885276, 2019).
tumor (continued). "However, the CD68+CD206+ TAMs were predominately located within the tumor-nest suggesting that the overall CD206 expression on the CD206+ (CD163−) macrophages (CD68+CD206++ plus CD68+CD206+) decreases as they near the tumor cells." (PMID 31477692, 2019). "iNOS+ and CD163+ cells were present in varying numbers in both IM and CT in all the tumours." (PMID 31358801, 2019). "But in tumor, a lot of TAMs were CD163 and HIF1α-positive, and less expressed HLA-DR and C9." (PMID 29900010, 2018). "Recently, we performed a retrospective study on primary tumours (n = 205) and paired metastatic lymph nodes (n = 127) from cervical cancer patients and showed PD-L1 expression by primary tumour cells as well as by tumour infiltrating and stromal CD163+ positive M2 macrophages." (PMID 30208866, 2018). "Thus, the upregulation of CD163 in intratumoral TAM-like cells in NOG-hIL-6 Tg mice indicates that the tumor microenvironment in progressive cancer was recapitulated in this mouse model, at least in part." (PMID 29456539, 2018). "Furthermore, in non-tumor tissues (mammary gland, liver, and oral mucosa), almost all CD163(+) cells were derived from the bone marrow." (PMID 30272010, 2018). "The localization and density of CD163+ M2-polarized TAMs and TEMs were quantified in the tumor central area (TCA) and tumor-infiltrating front (TIF) in human PDAC tissue (n = 106) and correlated to clinicopathological characteristics, tumor recurrence rates and patient survival." (PMID 30038715, 2018). "These markers (Foxp3, CD68, and CD163) were expressed on immune cells in the tumor stroma." (PMID 29506555, 2018). "Interestingly, the correlations between CD163+ pixels and either CD11b+ or CD11c+ pixels inside the tumor were r = 0.51 and r = 0.44, respectively, while other pairwise correlations were less than r = 0.2." (PMID 30619287, 2018). "In order to further investigate the immunological profile of the primary tumors in both the 4T1 + RAW264.7 and 4T1 inoculation group, immunohistochemistry for CD45, CD163, Ly6G and CD8a was performed on primary tumor sections at pre- (1 and 3 w p.i.)and metastatic (5 w p.i.)time points." (PMID 30111338, 2018). "Similar to clinical scenarios, it was observed that myeloid cells infiltrated the tumor, numerous cells within the tumor expressed CD14 and CD163 which are commonly associated as macrophage markers, and CD163+ cells were most likely M2-like macrophages as they were HLA-DRlow and CD206high." (PMID 29411049, 2018). "The pattern of TEMs and CD163+ TAMs displayed a preference for the tumor perivascular areas." (PMID 30038715, 2018). "At 3 w p.i. the CD163-positive tumor-recruited cells remained outside the tumor area, but strongly increased in the 4T1 inoculation group whereas in the 4T1 + RAW264.7 inoculation group a similar CD163-positive staining was observed at 3 w p.i. compared to 1 w p.i." (PMID 30111338, 2018). "A similar result was obtained when a macrophage signature comprising a subset of eight widely used markers (CD14, CD105, CD11b, CD68, CD93, CD33, IL-4R and CD163) for the mononuclear phagocyte system was used to identify tumours highly infiltrated by macrophages." (PMID 29921315, 2018). "In the patients’ tumor tissues, the nuclear Nrf2 positive cancer cells could also observe near the CD163 positive cells." (PMID 30180849, 2018). "Only few CD163-positive cells could be detected, which mainly comprise tumor-recruited anti-inflammatory/M2 macrophages." (PMID 30111338, 2018). "Furthermore, almost all CD163-positive TAMs and macrophages present in the non-tumor areas are derived from bone marrow." (PMID 30272010, 2018). "Besides promoting Treg function, CD163+ TAMs (M1-like) located around tumor/connective tissue also strongly secrete IL-10 and express more PD-L1 compared to other TAM subsets found within the tumor." (PMID 30619850, 2018).
tumor (continued). "In fact, numerous studies have revealed that the expression of M-CSF in tumor microenvironment is closely correlated with the number of CD163-positive M2 Mφs, which in turn contributes to the progression of several cancers, most likely by enhancing angiogenesis." (PMID 29559970, 2018). "An average 70% of CD68+ and CD163+ pixels were between 0 and 20 microns from the tumor edge." (PMID 30619287, 2018). "TNBC patients experiencing tumour recurrence show a decreased content of TILs and an increased number of CD163+ tumour-associated macrophages (TAMs) compared with those without recurrence." (PMID 29848327, 2018). "Moreover, AIRE by modulating the cytokine milieu skews the tumor-associated macrophage polarization towards M2 phenotype with increased CD206 and CD163 expression." (PMID 29795364, 2018). "In the CD163 and Nrf2 double staining of mice xenograft tumor tissues, the Nrf2 nuclear translocation could be observed not only in CD163-positive cells but also in the cancer cells around the CD163 positive macrophages." (PMID 30180849, 2018). "CD163 as a marker of macrophages, has been used to evaluate the status of tumor macrophages." (PMID 29152078, 2017). "Additionally, the macrophage differentiation at the primary tumor in the larynx was strongly CD163 positive supporting an immune permissive environment for tumor growth and metastasis." (PMID 28716144, 2017). "The tumor microenvironment often polarizes infiltrating macrophages towards a type 2, or M2 phenotype, that is characterized by expression of various cysteine-rich, scavenger receptors, including CD163." (PMID 28716144, 2017). "CD163 was expressed in some tumor cells at the mucosa layer." (PMID 29152078, 2017). "Consistent with previous results, a large numbers of CD163 positive macrophages could be found in tumor stroma." (PMID 29152078, 2017). "While when tumor cells broken lamina propria of the mucosa, CD163 significantly increased." (PMID 29152078, 2017). "Based on the cell fusion theory and the assumption that macrophage–cancer cell fusion creates hybrids expressing phenotypic characteristics of macrophages, we used the macrophage-specific marker CD163 as a surrogate marker for detecting fusion events in a clinical tumor material." (PMID 28881654, 2017). "We also analyzed the infiltration of CD68- and CD163-positive macrophages in tumor tissue of AITL." (PMID 29100307, 2017). "So we tried to examine whether CD163 could be used as a potential indicator to evaluate the status of tumor microenvironment." (PMID 29152078, 2017). "In the present study, we aimed to evaluate whether assessment of CD8+ and CD163+ cell densities in single or combined tumor regions (TC and IM) improves the prognostic value of immunoscoring in BCa and allows refinement of conventional prognostic parameters." (PMID 28428887, 2017). "In addition, several studies focused on the tumor-promoting M2 phenotype using more specific markers, including CD163 and CD204, or double staining of CD68 and CD163." (PMID 27144518, 2016). "In each of these tumor specimens, there was extensive CD163 staining." (PMID 27834402, 2016). "Also our data suggest the expression of CD163 in tumor cells was significantly correlated with the expression of E-cadherin and vimentin." (PMID 26769084, 2016). "However, the number of CD68-positive macrophages and CD163-positive macrophages in tumor stroma, and the levels of CD68 and E-cadherin expression in tumor cells did not shown any significant correlation with overall survival." (PMID 26769084, 2016).
tumor (continued). "Furthermore, to make sure THP-1 derived M2 macrophages existed in xenografted tumor lesion, we've verified using IHC with the detection of CD163." (PMID 27765933, 2016). "However, the frequencies of macrophages that were independently CD33+, CD163+ or CD206hi were significantly lower in tumor compared with NTB." (PMID 27195119, 2016). "However, in human tumor specimens we identified CD163+ macrophage networks that coincide with PAS+ stain." (PMID 27834402, 2016). "Furthermore, the expression levels of CD163 in tumor cells (P = 0.001), vimentin both in tumor (P = 0.006) and at the tumor invasion front (P = 0.002) had a worse prognostic impact on the survival rate." (PMID 26769084, 2016). "Indeed, we found that, when compared to HGSOC, LGSOC patients showed a lower density of tumor-infiltrating CD68+ macrophage along with an attenuated M2-skewed (CD163+) phenotype." (PMID 27462782, 2016). "Macrophage antigens CD163 expressed in tumor cells may be a heterotypic cell fusion between the TAMs and tumor cells and this fusion may enhance the metastatic potential of tumor cells." (PMID 26769084, 2016). "Intriguingly, classical M2 markers including Cd206 (Mrc1), Cd163, Pdl2 (Pdcd1lg2), Ccr3, Arg1 and many others were all markedly downregulated in TAMs isolated from the St2−/− background as compared with those isolated from tumours grown in wt mice." (PMID 27150562, 2016). "Such novel results are supported by a previous study that CD163 expressing tumor cells may establish a subpopulation of tumor cells, which could exhibit an EMT-correlated phenotypic shift and increased metastatic ability induced by TAMs." (PMID 26769084, 2016). "Our data showed various ratios of CD163-positive macrophages in DLBCL tumour tissues." (PMID 27464733, 2016). "Their phenotype is shaped by tumor microenvironment towards immunosuppressive state associated with increased production of tumor growth-promoting cytokines, decreased antigen-presenting properties, and elevated expression of scavenger receptors (SR) including SR-A, CD206, CD163, and stabilin-1." (PMID 27105498, 2016). "Notably, these surface markers are highly expressed on M2 macrophages and human breast TAMs, and tumor expression of CD163 is directly correlated with early distant recurrence and reduced patient survival." (PMID 26918785, 2016). "In addition, the relationship between CD68+ and CD163+ TAMs in the tumor microenvironment of adult cHL and other clinical characteristics was also examined." (PMID 27745550, 2016). "The transcript levels of the M2 macrophage markers Cd206, Cd163, Il4ra were all increased, whereas the levels of M2 markers Fizz1 and Ym1, were decreased in the tumor-infiltrating myeloid cells following Vorinostat, suggesting a mixed M1/M2 macrophage phenotype." (PMID 27471639, 2016). "Moreover, naïve monocytes co-cultured with tumor cells showed decreased expression of CD163, the scavenger receptor expressed on M2 suppressive microphages, only in the presence of cetuximab (p = 0.004)." (PMID 26579227, 2015). "In those tumor types, the elevated M-CSF and CD163 expression correlates with higher tumor grade." (PMID 26243145, 2015). "CD163 is a scavenger receptor on cells of the monocytic lineage, with weak expression on peripheral blood monocytes and abundant expression on the majority of tumor-derived macrophages." (PMID 25871392, 2015). "IL-17 and peritumoral CD163 may exert important roles in the inflammatory tumor microenvironment and facilitate tumor progression and recurrence." (PMID 26205001, 2015). "The fast growing locally aggressive and metastatic MatLyLu tumors appear to be particularly effective in recruiting macrophages, of which many are of the tumor-stimulating M2 phenotype (CD163 positive), to the tumor, to the invasive front and to the surrounding tumor-bearing organ." (PMID 26536349, 2015). "Cancer indications with proven negative correlation between tumor-associated macrophage CD163 expression and survival." (PMID 26111002, 2015).